C8orf76 (chromosome 8 open reading frame 76)
Synonyms: FLJ14825
Tractability: PROTAC: ubiquitination databases record sites on it.
Gene: Protein-coding gene on chromosome 8 (123,219,967 to 123,241,384, reverse strand). Ensembl gene ENSG00000189376.
Subcellular location (Human Protein Atlas): Nucleoplasm; Cytosol
Genetic constraint (gnomAD): Loss-of-function variants: 48 observed, 41.01 expected, observed/expected ratio (o/e) 1.17, 90% interval 0.93 to 1.49. The upper end of that interval is the gene's LOEUF score, 1.49, which puts it in group 6 of 6, group 1 being the genes least tolerant of losing a copy. Missense variants: 460 observed, 450.34 expected, observed/expected ratio (o/e) 1.02, 90% interval 0.95 to 1.1. Synonymous variants: 166 observed, 169.67 expected, observed/expected ratio (o/e) 0.98, 90% interval 0.86 to 1.11.
Homologues: Orthologues: chimpanzee C8H8orf76 (99% identical), macaque C8H8orf76 (96% identical), dog C8orf76 (89% identical), pig C8orf76 (82% identical), rabbit C8orf76 (78% identical), guinea pig C8orf76 (72% identical), mouse 9130401M01Rik (68% identical), rat C7h8orf76 (66% identical), tropical clawed frog c7h8orf76 (40% identical), zebrafish zgc:101716 (29% identical).
Diseases named in the same sentence as C8orf76 in open-access papers:
C8orf76 is named in the same sentence as 8 diseases in open-access papers, as found by Europe PMC text mining. Sharing a sentence is not in itself a finding about the gene and the disease. The quoted sentences say what the papers report.
gastric cancer (3 papers, 2022 to 2023). A primary or metastatic malignant neoplasm involving the stomach. "A previous study confirmed that C8orf76 acted as a tumor-promoting role in gastric cancer that transactivated lncRNA DUSP5P1 by directly binding to the DUSP5P1 promoter and activating the MAPK/ERK signaling pathway." (PMID 35884471, 2022). "Chromosome 8 open reading frame 76 (C8orf76), located in 8q24.13–24.3, was identified as a novel oncogene in gastric cancer." (PMID 35884471, 2022). "C8orf76 plays a crucial role in the occurrence of gastric cancer and can serve as an independent prediction model to evaluate the clinical outcome of patients with gastric cancer." (PMID 37827692, 2023). "qRT-PCR verified that ZFPM2-AS, NUP107 and C8orf76 were highly expressed in gastric cancer cells." (PMID 35416526, 2022).
liver cancer (1 paper, 2022). An epithelial or non-epithelial malignant neoplasm that arises from the liver. "Based on the data from The Cancer Genome Atlas (TCGA) datasets, high C8orf76 mRNA expression was found in liver cancer patients compared with corresponding paracancerous tissues." (PMID 35884471, 2022). "We provided the first evidence showing that C8orf76 was involved in ferroptosis regulation via transcriptional SLC7A11 activation to investigate the concrete mechanism of C8orf76 during liver cancer progression." (PMID 35884471, 2022). "Here, we reported for the first time that C8orf76 gene expression levels were frequently upregulated in liver cancer and significantly correlated with HCC development." (PMID 35884471, 2022). "However, expression levels of C8orf76 were found to be relatively high in liver cancer, whereas it was minimally expressed in adjacent normal tissues." (PMID 35884471, 2022). "Importantly, we confirmed the effect of C8orf76 on liver cancer ferroptosis by altering C8orf76 expression." (PMID 35884471, 2022).
cancer (4 papers, 2022 to 2025). A tumor composed of atypical neoplastic, often pleomorphic cells that invade other tissues. "A search for novel genetic variants of C3orf70, C8orf33, C8orf76 and C8orf82 associated with systemic diseases, including cancers, is of practical interest for medical genomics." (PMID 37373333, 2023). "At least the function of genetically unstable C8orf76 is associated with cell proliferation, so amplification of the C8orf76 gene in cancers may be an independent risk factor of enhanced cell proliferation." (PMID 37373333, 2023). "It is interesting to note that GA frequency is up to 6% in C3orf70, C8orf33, C8orf76 and C8orf82 genes according to the most affected cancer types." (PMID 37373333, 2023). "Since C8orf76 was regarded as an oncogene in clinical samples and public cancer data, we first evaluated the effects of C8orf76 on HCC tumor growth in vitro." (PMID 35884471, 2022). "Subsequently, to probe the effect of NUP107 and C8orf76 in cancer patients’ survival, we divided all samples into high-expression and low-expression groups and compared the OS rate of the other 32 cancer types." (PMID 35416526, 2022). "To date, the exact molecular mechanisms of C8orf76 in most cancers including HCC are unknown and need to be investigated in depth." (PMID 35884471, 2022). "In addition, a better comprehensive understanding of the potential role of C8orf76 in HCC helped us develop novel therapeutic strategies for this intractable cancer." (PMID 35884471, 2022). "In this study, we identified C8orf76 as a novel SLC7A11 gene regulator at the transcriptional level, which provided new insights into the mechanism of ferroptosis in cancer." (PMID 35884471, 2022). "More interestingly, NUP107 and C8orf76 might play a significant role in the TIME of GAC and could be a potential biomarker for cancer prognosis." (PMID 35416526, 2022).
tumor (4 papers, 2022 to 2025). "Kyoto Encyclopedia of Genes and Genomes (KEGG) enrichment revealed that critical tumor-associated pathways were significant difference while C8orf76 knockdown." (PMID 35884471, 2022). "The correlation between C8orf76 expression and diagnostic, prognosis, genetic alteration, mRNA modification, DNA methylation, lncRNA-miRNA-C8orf76 regulatory network, immune cell infiltration, and anti-tumor drugs response were explored to evaluate the potential roles of C8orf76." (PMID 40206508, 2025). "Recent studies reported C8orf76 as a tumor-promoting factor that promotes cell proliferation and metastasis of GC cells." (PMID 35416526, 2022). "Chromosome 8 open reading frame 76 (C8orf76), a novel gene located in the nucleus, is highly expressed in many tumor types." (PMID 35884471, 2022). "Then, we attempted to explore the extent to which ferroptosis stimulation could influence tumor cells after C8orf76 upregulation." (PMID 35884471, 2022). "Moreover, we also found that C8orf76 was highly expressed in tumor and portal vein tumor thrombosis (PVTT) tissues compared to adjacent benign tissues according to our previous RNA-seq analysis." (PMID 35884471, 2022). "Transcription factor GATA3, which can bind to the C8orf76 gene promoter, is expressed at an early stage of thymus development and participate in thymocyte differentiation as well as in control lymphoid cell differentiation, being a tumor suppressor in B-cell lymphomagenesis." (PMID 37373333, 2023). "Moreover, although C8orf76 overexpression did not affect tumorigenesis under normal conditions, it increased resistance to lipid disturbance and ferroptosis triggered by erastin or sorafenib, which further facilitated HCC cell growth and tumor progression." (PMID 35884471, 2022).
C8orf76 also shares sentences with these, for which no sentence is quoted: breast carcinoma (1 paper); endometrial cancer (1); lung adenocarcinoma (1); renal carcinoma (1).